UCA1 (urothelial cancer associated 1)
Diseases named in the same sentence as UCA1 in open-access papers (continued):
Sharing a sentence is not in itself a finding about the gene and the disease.
bladder cancer (continued). "Only 12 studies focused on exosomal multiple-ncRNA assay in bladder cancer detection, while 34 studies investigated single-ncRNA assay, of which 7 studies probed into the diagnostic value of exosomal single UCA1 in bladder cancer and 6 studies explored single MALAT1." (PMID 38227115, 2024). "Urothelial cancer associated 1 (UCA1) is a lncRNA upregulated in bladder cancer cells." (PMID 37533667, 2022). "A similar study demonstrated that hypoxic bladder cancer cells remodel the TME to enhance tumor growth and development by expressing the oncogenic long noncoding RNA (lncRNA)-UCA1-enriched exosomes, which also appears as a possible diagnostic biomarker in human serum for bladder cancer." (PMID 36233088, 2022). "UCA1 mRNA expression shows a significant association with the stage and grade of bladder cancer." (PMID 36685879, 2022). "Interestingly, long non-coding ribonucleic acid (lncRNA) urothelial carcinoma-associated 1 (UCA1) was highly expressed in bladder cancer cells." (PMID 33610185, 2021). "Urothelial cancer associated 1(UCA1) was first identified in bladder cancer." (PMID 33477833, 2021). "Furthermore, when comparing patients with bladder cancer with healthy controls, the combination of UCA1, circFARSA and circSHKBP1 has better diagnostic performance compared with UCA1 alone." (PMID 33777227, 2021). "The lncRNA, urothelial carcinoma associated 1 (UCA1) has been studied in a broad range of cancer types such as breast cancer, melanoma, gastric cancer, colorectal cancer, bladder cancer and others, and various mechanism underlying the regulatory role of UCA1 in cancer development have been proposed." (PMID 31596734, 2019). "In addition, the diagnostic meta-analysis concluded that abnormally expressed UCA1 can function as potential diagnostic markers for bladder cancer." (PMID 29899709, 2018). "Urothelial Carcinoma Associated 1 (UCA1) was an originally identified lncRNA in bladder cancer." (PMID 28380443, 2017). "Here, we aim to clarify whether hypoxia affects tumor growth and progression by transferring long non-coding RNA-urothelial cancer-associated 1 (lncRNA-UCA1) enriched exosomes secreted from bladder cancer cells." (PMID 28841829, 2017). "The pooled assessment outcomes for 6 studies were as follows: sensitivity, 0.83 (95% CI= 0.80-0.86); specificity, 0.83 (95% CI=0.80-0.86); DOR, 0.83 (95% CI=0.80-0.86); and area under the curve (AUC), 0.83 (95% CI=0.80-0.86), indicating a high diagnostic accuracy of urinary UCA1 for bladder cancer." (PMID 28038452, 2017). "The role of UCA1 in bladder cancer was associated with ROS (reactive oxygen species) metabolism." (PMID 29147648, 2017). "Our analysis indicated that urine UCA1 as a non-invasive diagnostic marker for bladder cancer." (PMID 28038452, 2017). "Additionally, urinary UCA1 can be used as a non-invasive diagnostic marker for bladder cancer as revealed by a meta-analysis." (PMID 28038452, 2017). "Human UCA1 (urothelial carcinoma associated 1) is a lncRNA that was first identified in human bladder carcinoma, and whose oncogenic effect may be related to glucose metabolism." (PMID 27329842, 2016). "The linc-RNA UCA1 (urothelial carcinoma associated 1) is an lncRNA identified as a potential biomarker for bladder cancer, with higher levels detected in tumor tissue and the potential to discriminate between bladder/urothelial cancer and cancers of other anatomical origins." (PMID 26516918, 2015). "Urothelial carcinoma associated 1 (UCA1), a novel lncRNA, has been reported to play a potential role in the progression of bladder cancer and could serve as a biomarker for diagnosis of bladder cancer." (PMID 24993775, 2014). "Subsequent research in bladder cancer cell lines showed that UCA1 can promote cell proliferation, but the underlying mechanism remains unknown." (PMID 24993775, 2014). "However, the general function and underlying mechanisms of UCA1 in bladder cancer cells have remained elusive and require further investigation." (PMID 24993775, 2014).
bladder cancer (continued). "High expression of UCA1 in bladder cancer has suggested it may serve as a potential diagnostic molecular marker for bladder cancer." (PMID 24993775, 2014). "In addition, the study by our laboratory showed that there are three splicing variants of the UCA1 gene existing in bladder cancer cells." (PMID 24069250, 2013). "Similarly, overexpressed lncRNA, namely, urothelial carcinoma associated 1 (UCA1) affects cell proliferation and invasion in bladder cancer." (PMID 23843741, 2013). "Simultaneously, UCA1 is associated with clinical parameters and prognosis of cancer patients and may be a potential diagnosis biomarker in gastric cancer, hepatocellular cancer and bladder cancer." (PMID 28423704, 2017). "Thus we assumed that UCA1 gene expression may be associated with the activation of Akt pathway which is involved in the Ets-2 mediated anti-apoptosis process in bladder cancer cells." (PMID 24069250, 2013). "Beyond LINC01094, other lncRNAs—including MALAT1, UCA1, and XIST, among others—have also been implicated in bladder cancer progression or metabolic reprogramming." (PMID 40438104, 2025). "Recently, a label-free biosensor based on nanopore technology was developed for the detection of long non-coding RNAs (lncRNAs), using UCA1 as a model biomarker for bladder cancer." (PMID 40868379, 2025). "Urinary exosomes from 42 bladder cancer patients were collected and quantified for seven lncRNAs (UCA1, H19, MALAT1, TUG1, GAS5, RMRP, and LINC01517), showing increased expression of RMRP, UCA1, and MALAT1 in bladder cancer patients." (PMID 40075875, 2025). "UCA1 promotes the initiation and progression of bladder cancer by interacting with BRG1, thereby repressing the expression of p21 and enhancing cell proliferation." (PMID 41179679, 2025). "UCA1 was first discovered in bladder cancer, but it was demonstrated that overexpression of UCA1 also promotes the migration, invasion, and metastasis of other cancer cells, including HNSCC." (PMID 41020820, 2025). "In bladder cancer, UCA1 plays a role in glutamine metabolism and blocks ROS generation by serving as a sponge for miR‐16 and increasing the levels of miR‐16, which targets GLS2." (PMID 40567251, 2025). "CEBPB is involved in the transcriptional regulation of LncRNA UCA1, promoting its high expression and thereby promoting the proliferation of bladder cancer cells." (PMID 38710698, 2024). "UCA1 was included in the panel because of its documented correlation with different tumors, including bladder cancer." (PMID 38846969, 2024). "Its performance is comparable or even better than that of UCA1, another lncRNA that has long been established to be involved in bladder cancer progression." (PMID 38846969, 2024). "lncRNA UCA1 increases the chemoresistance of cisplatin in bladder cancer treatment by activating the WNT signaling." (PMID 38695942, 2024). "We have shown that the lncRNA SUMO1P3 is increased in urine from patients with high grade NMIBC and MIBC and that it is likely to be good candidate to predict bladder cancer progression if used alone or in combination with UCA1 or with miRNA320a." (PMID 38846969, 2024). "Clinical tumor diagnostic markers for BC include Bladder Tumor Antigen (BTA), urine cytology (UroVysion), Urothelial Cancer-Associated Antigen 1 (UCA1), Cytokeratin-19 Fragment (CYFRA 21-1), and Bladder Cancer MCM6 marker." (PMID 39071712, 2024). "This study highlights that the UCA1-miR-195-ARL2 signaling axis sustains mitochondrial metabolism in bladder cancer." (PMID 38544804, 2024). "UCA1 regulates embryonic development and bladder cancer invasion and advances as a regulator of the expression of different genes involved in tumorigenesis and embryonic development." (PMID 38534656, 2024). "Bladder cancer cells overexpressing UCA1 or TWIST1 had reduced migratory capacity after MPA treatment or knockdown of IMPDH1/2." (PMID 37215997, 2023).
bladder cancer (continued). "As miR-16 binds to GLS and inhibits its transcription, UCA1 promoted the proliferation and migration of bladder cancer cells through acting as a ceRNA to upregulate GLS2 expression." (PMID 37127605, 2023). "UCA1 is specifically overexpressed in bladder cancer and regulates guanine nucleotide metabolism in these tumors." (PMID 37215997, 2023). "In nude mice, overexpression of UCA1 promotes the proliferation, migration, invasion, anti-apoptosis, tumorigenicity, and treatment resistance of bladder cancer cells 15-18." (PMID 37215997, 2023). "Overexpression of TWIST1 or IMPDH1/2 in 5637 cells knockdown UCA1 enhanced migration of bladder cancer cells." (PMID 37215997, 2023). "Urothelial carcinoma antigen 1 (UCA1) was first discovered in bladder cancer, which promoted tumor progression in bladder and prostate cancer.With further research, the role of UCA1 in gastrointestinal cancers has also been reported." (PMID 37564930, 2023). "LncRNA UCA1, which is firstly identified in human bladder cancer, has been showed to be a tumor promoter in pancreatic cancer." (PMID 36741256, 2023). "Our previous research confirmed that UCA1 is involved in bladder cancer cells' glucose and glutamine metabolism 15-18." (PMID 37215997, 2023). "Urothelial carcinoma antigen 1(UCA1), a long noncoding RNA (lncRNA) that was first reported in bladder cancer, acts as an oncogene." (PMID 37564930, 2023). "In bladder cancer cells, UCA1 regulates the hexokinase glycolytic enzyme 2 (HK2), which significantly enhances aerobic glycolysis 19, 20, and it participates in the metabolic remodeling of cancer cells." (PMID 37215997, 2023). "In conclusion, the purpose of this study is to examine how UCA1 regulates guanine nucleotides to facilitate bladder cancer progression in bladder cancer cells." (PMID 37215997, 2023). "The rescue experiment verified the regulatory of UCA1 on guanine nucleotide in bladder cancer cells." (PMID 37215997, 2023). "Based on our findings we confirmed that IMPDH1 and IMPDH2 are target genes of UCA1 controlling purine metabolism in bladder cancer." (PMID 37215997, 2023). "The urothelial cancer-associated 1 (UCA1) enhanced mitochondrial function and bladder cancer cell viability through the UCA1/miR-195/ARL2 axis." (PMID 36831498, 2023). "UCA1 aided in the regulation of glutamine metabolism and the production of reactive oxygen species (ROS) in bladder cancer cells." (PMID 37245177, 2023). "UCA1 by regulating the high mobility group box 1 (HMGB1) pathway enhances the properties of bladder cancer invasion and metastasis." (PMID 36685879, 2022). "For example, exogenous lncRNA UCA1 increased the invasiveness of cancer cells and worked in cisplatin resistance to bladder cancer therapy." (PMID 35645836, 2022). "UCA1 overexpression has been reported in different types of cancer, such as breast cancer, ovarian cancer, bladder cancer, and hepatocellular carcinoma." (PMID 35901079, 2022). "In bladder cancer, UCA1 increases ATF2 expression by binding miR‐204 and promotes cancer progression." (PMID 35289508, 2022). "UCA1 is known to be transported via exosomes and leads to bladder cancer progression under hypoxic conditions." (PMID 36685879, 2022). "In bladder cancer cells, UCA1 activates the transcription factor CREB, which induces the expression of miR-196a-5p, thereby promoting cancer cell proliferation, migration, invasion, and gemcitabine resistance." (PMID 36499136, 2022). "Ets-2 transcriptionally regulates UCA1, resulting in activation of the Akt signalling pathway and suppresses the bladder cancer cell apoptosis." (PMID 37533667, 2022). "Urothelial cancer-associated 1 (UCA1), with a 1.4 kb long transcript, is a long noncoding RNA (lncRNA) that was identified in a bladder cancer cell line." (PMID 35132340, 2022). "More importantly, by inducing EMT to accelerate the growth and progression of cancer, hypoxia can enhance the mutual movement of lncRNA UCA1 into the exon-mediated bladder cancer cells." (PMID 35444701, 2022).
bladder cancer (continued). "The overexpression of UCA1 was shown to abrogate apoptotic cell death and facilitate acquired resistance during anti-cancer therapy in bladder cancer cells." (PMID 36685879, 2022). "UCA1 was initially considered an oncogenic lncRNA in bladder cancer and was revealed to be overexpressed in multiple cancers in subsequent studies." (PMID 34976187, 2022). "UCA1 transfer via EVs obtained from hypoxic bladder carcinoma cells promoted tumor cell proliferation, migration, and invasion in recipient cells via mechanisms that involved epithelial-mesenchymal transition, a process relevant for cancer progression." (PMID 35966580, 2022). "The AUC value of circSHKBP1 and lncRNA UCA1 signature to discriminate patients with bladder cancer from controls was 0.804, and that of this signature was 0.870 with respect of low-grade tumors." (PMID 33816529, 2021). "It was reported that lncRNA UCA1 participated in the malignant progression, drug resistance and metabolism reprogramming of bladder cancer." (PMID 33849550, 2021). "Cisplatin and gemcitabine resistance in bladder cancer cells is mediated by UCA1-CREB-miR-196a-5p paradigm." (PMID 33777227, 2021). "UCA1, which is overexpressed in bladder cancer, specifically induces Glutaminase 2 (GLS2) by sponging miR-16, and can also activate AKT by recruiting E1A Binding Protein P300 (EP300) and lead to bladder cancer cell growth." (PMID 34422802, 2021). "C/EBPβ, a TF regulating the expression of the lncRNA UCA1, upregulates lncRNA UCA1 expression and subsequently promotes bladder cancer proliferation." (PMID 34930912, 2021). "Accordingly, cotreatment with anti-PD-1 and anti-UCA1 retarded tumor growth and increased the survival of xenografted mice, demonstrating synergistic efficacy in bladder cancer." (PMID 34496886, 2021). "HIF-1α was shown to regulate the expression of UCA1 in bladder cancer cells by binding to two hypoxia responsive elements (HREs) in the promoter of UCA1, leading to its activation under hypoxic conditions." (PMID 34054950, 2021). "In gastric cancer, ZFAS1 induces cell cycle, apoptosis, and EMT, while UCA1 has similar effects in bladder cancer." (PMID 34067896, 2021). "The sensitivity of MALAT1, SNHG16 and UCA1 is 0.567, 0.642, 0.83; the specificity of MALAT1, SNHG16 and UCA1 is 0.675, 0.650, 0.86; the ROC curve AUC of MALAT1, SNHG16 and UCA1 used for bladder cancer is 0.635, 0.679, 0.86." (PMID 34422802, 2021). "In bladder cancer cells, UCA1 regulates the glutamine metabolism and antioxidant defense by inhibiting miR-16, which targets GLS2 for translational inhibiting and reduced GLS2 expression." (PMID 33849550, 2021). "Specifically, UCA1 is considered a sensitive and specific biomarker for bladder cancer and a promising therapeutic target for colorectal cancer." (PMID 34233576, 2021). "have found that the expression of UCA1 is elevated in the hypoxic bladder cancer cell-derived exosomes compared with that of the healthy donors, which promotes bladder tumor growth though epithelial–mesenchymal transition (EMT)." (PMID 34212174, 2021). "In one study, knockout of lncRNA UCA1 was found to promote apoptosis of 5637 bladder cancer cells; activate DCs; induce cytokine secretion, including IL-6, IL-12, IL-23 and TNFα; and more importantly, elevate PD-L1 expression." (PMID 34496886, 2021). "Although UCA1 was initially identified in human bladder cancer cell line, subsequent studies revealed that it is overexpressed in a wide range of human cancers, including CRC." (PMID 34809621, 2021). "UCA1 is an oncofetal gene with oncogenic functions reported in many cancers; for instance, an increase in UCA1 expression promotes proliferation and metastases formation in bladder cancer and is a factor of poor prognosis in colorectal cancer and glioma." (PMID 34160887, 2021). "As already observed in HCC and esophageal cancers, lncRNA UCA1 also promotes glycolysis in bladder cancer cells." (PMID 33652661, 2021).
bladder cancer (continued). "UCA1 had been abundantly investigated as a non-invasive biomarker for various types of cancer, in particular for bladder cancer, both in blood and urine." (PMID 33477833, 2021). "And targeting lncRNA UCA1 induced intratumoral interferon gamma-dependent programmed cell death ligand 1 expression in vivo, thereby synergistically enhancing the anti-bladder cancer activity of immune checkpoint blockade of PD-1." (PMID 34777462, 2021). "LncRNA UCA1 present in exosomes from bladder cancer cells under hypoxic conditions was responsible for promoting EMT and reshaping the tumor microenvironment." (PMID 34067896, 2021). "These drugs provide the possibility of chemotherapy-related clinical applications, and studies have demonstrated that UCA1 knockdown can reverse multidrug resistance in retinoblastoma and bladder cancer." (PMID 33777227, 2021). "The relationship between lncRNA UCA1 and miR-143 has been revealed in the progression of both breast cancer and bladder cancer." (PMID 33591946, 2021). "UCA1 functions as a tumorigenic lncRNA in different cancers such as bladder cancer, breast cancer, lung cancer, melanoma, and colorectal cancer." (PMID 34733326, 2021). "In bladder cancer under hypoxic conditions, the bladder cancer cell line 5637 can release more exosomes containing lncRNA UCA1." (PMID 34819615, 2021). "In previous studies, UCA1 has been identified to serve as a tumorigenic lncRNA in different cancer types such as bladder cancer, breast cancer, lung cancer, melanoma, and colorectal cancer." (PMID 34733326, 2021). "For example, long non-coding RNA UCA1 sensibilize cisplatin/gemcitabine resistance by regulation of miR-196a-5p in bladder cancer cell." (PMID 32202509, 2020). "Increased UCA1 expression by HIF-1α upregulation was also reported in osteosarcoma as well as hypoxic bladder cancer cells through HREs in the UCA1 promoter region." (PMID 32640630, 2020). "UCA1 was first discovered in bladder cancer and has been proved to promote the migration and invasion of bladder cancer cells." (PMID 33520725, 2020). "Similar to the results among Iranian bladder cancer, it has been reported that the UCA1 expression was significantly up-regulated in CRC tissues compared with normal margins." (PMID 31956395, 2020). "The authors concluded that the effects in bladder cancer cells mediated by UCA1/miR-195/ARL2 are a consequence of mitochondrial metabolism modulation, which regulates cancer cell survival (Li H.-J." (PMID 32426352, 2020). "Apart from CRC, the oncogenic function of UCA1 was also embodied in non-small cell lung cancer, bladder cancer, breast cancer, tongue squamous cell carcinoma and esophageal cancer, a portion of which were achieved through its interplay with specific miRNAs." (PMID 32143722, 2020). "It had been reported in the literature that UCA1 was involved in the cisplatin resistance mechanism of ovarian cancer and bladder cancer." (PMID 32249461, 2020). "The UCA1 lncRNA is also involved in cell proliferation, migration, invasiveness, and drug resistance of bladder cancer cells." (PMID 32517366, 2020). "The increased level of lncRNA UCA1 activated Wnt signaling and resulted in the cisplatin resistance of bladder cancer cells in a Wnt6-dependent manner." (PMID 31143372, 2019). "Studies had found UCA1 was dysregulated and participated in the development of a few cancers including hepatocellular carcinoma, pancreatic cancer, bladder cancer." (PMID 31133028, 2019). "They found a significantly higher expression of LINC00355, UCA1-203, and MALAT1 and a decreased UCA1-201 expression in bladder cancer patients compared to the other two groups." (PMID 35582278, 2019). "Recent observations indicate that lncRNA UCA1 promotes migration and invasion in bladder cancer cells." (PMID 31293964, 2019). "UCA1 was first identified in bladder cancer and functions to regulate embryonic development and promote bladder cancer invasion and migration." (PMID 31596734, 2019).